MMP2 (matrix metallopeptidase 2)
Diseases named in the same sentence as MMP2 in open-access papers (continued):
Sharing a sentence is not in itself a finding about the gene and the disease.
gastric cancer (302 papers, 1996 to 2025). A primary or metastatic malignant neoplasm involving the stomach. "High expression of MMP-2 is generally indicative of a highly invasive tumor and is closely linked to metastasis and poor prognosis in breast cancer, gastric cancer, and BC as well." (PMID 40303286, 2025). "MMP2 inhibitor also attenuated the increased invasion and migration ability of gastric cancer cells caused by low expression of CDK5RAP3." (PMID 35999359, 2023). "The use of an MMP2 inhibitor attenuated colony formation caused by gastric cancer cells with low expression of CDK5RAP3." (PMID 35999359, 2023). "The elevated levels of VEGF and VEGFR-1, as well as MMP-9 and MMP-2, have been linked to the formation of VM in gastric cancer tissues." (PMID 35747793, 2022). "Overexpression of MMP-2 is a prominent feature of gastric cancer, closely associated with gastric cancer metastasis." (PMID 35267781, 2022). "We also found that higher protein level of MMP2 was associated with survival of patient s in our cohort of gastric cancer." (PMID 35397606, 2022). "With the utility of TCGA data, we found that higher mRNA level of MMP2 was associated with poor survival of gastric cancer by Kaplan–Meier curve." (PMID 35397606, 2022). "In this study, using TCGA data, we found that higher mRNA level of MMP2 was associated with patient’s survival in gastric cancer." (PMID 35397606, 2022). "Co-expression of MMP-2 with uPA, uPAR, PAI-1 or PAI-2 is seen in gastric cancer, with co-expression of MMP-2 and uPAR associated with worse OS." (PMID 34439251, 2021). "For example, propranolol, a non-selective adrenergic blocker, can cause cell cycle arrest and induce apoptosis in gastric carcinoma cells by blocking nuclear factor-kB (NF-kB), MMP2/9, VEGF, and cyclooxygenase-2 (COX-2)." (PMID 33670813, 2021). "Omental adipocytes enhance the invasiveness of gastric cancer cells by oleic acid-induced activation of PI3K-Akt signaling pathway involving associated upregulation of the key pro-invasion factor MMP2." (PMID 32780245, 2020). "Overexpression of MMP-2 has been associated with increased tumor metastasis and worse prognosis in several cancers, including gastric cancer." (PMID 29385675, 2018). "Specifically, MMP2 expression is associated with gastric cancer progression and lymph node metastasis." (PMID 27588484, 2016). "An increase in MMP-2 levels and the presence of the active type of MMP-2 were closely associated with the ability of invasion and metastasis of gastric cancer." (PMID 24959277, 2014). "We showed previously that high tumour levels of MMP-2 in gastric carcinomas were consistently associated with a worse survival." (PMID 18506186, 2008). "Our study shows that an enhanced MMP-2 level is consistently and more strongly associated with prognosis of gastric cancer patients than other MMPs or TIMPs." (PMID 16538217, 2006). "We previously reported significantly enhanced MMP and TIMP levels in gastric carcinomas, but only MMP-2 was independently associated with a poor overall survival of the patients." (PMID 16940985, 2006). "BK also causes MMP2 secretion through the ERK1/2 pathway in gastric cancer cells." (PMID 39519260, 2024). "Our results also showed that signaling pathways associated with MMP-2, -9, and uPA regulation are vital in gastric cancer cells, and sinulariolide efficiently blocks gastric cancer metastasis via targeting the signaling pathways driving the processes of gastric cancer advancement." (PMID 31783709, 2019). "The serum MMP-2 level was also found to be associated with the development of gastric cancer." (PMID 29949618, 2018). "It was found that expression of BGN (HR 1.9 [1.56–2.32], P = 1.3 × 10–10) was associated with worse overall survival (OS) for gastric cancer patients, as well as MMP2 (HR 1.78 [1.47–2.16], P = 2.6 × 10–9), COL1A1 (HR 1.49 [1.22–1.81], P = 8.2 × 10–5) and FN1 (HR 1.46 1.23–1.74], P = 1.3 × 10–5)." (PMID 29050278, 2017).
gastric cancer (continued). "Furthermore, our previous study and another study have demonstrated that among the MMPs, MMP-2 expression is associated with the invasive phenotype of gastric cancer cells." (PMID 25621065, 2015). "In summary, our study demonstrates that CAFs may promote gastric cancer cell migration and invasion via increased MMP-2 production caused by TAGLN upregulation." (PMID 23510049, 2013). "Because some gene polymorphisms of MMPs and TIMPs have been found to be related to disease susceptibility and changed gene transcription in vitro, we investigated whether gastric cancer is associated with SNPs of MMP-2, -7, -8 and -9, or their inhibitors TIMP-1 and TIMP-2." (PMID 16940985, 2006). "Mechanistic studies have shown that ARL6IP5 insufficiency and up-regulation of matrix metalloproteinase-2 (MMP-2) can increase tumor micro vessel density in gastric cancer." (PMID 40253526, 2025). "No notable genetic alterations distinguishing the two groups were observed for other gastric cancer‐associated genes, such as BIRC5, MET, and MMP2." (PMID 41407509, 2025). "Han and Tsai found that inhibiting the expression of VEGF in gastric cancer cells can reduce the expression of MMP2 and MMP9." (PMID 40563539, 2025). "For example, K672/K799 succinylation of FBN1 protein in gastric cancer can inhibit ECM degradation mediated by MMP2-2 and promote tumor cell invasion." (PMID 40865948, 2025). "A study investigating the impact of ERα expression in CAFs in gastric cancer confirmed increased expression of matrix metalloproteinase-2 (MMP2) and matrix metalloproteinase-9 (MMP9)." (PMID 41301715, 2025). "Studies indicate that the expression of both MMP-9 and MMP-2 correlates with the expression of LOX in gastric cancer biopsies." (PMID 40906383, 2025). "Several meta-analyses and bioinformatic studies have found that the overexpression of MMPs, like MMP2 and MMP9, is associated with a poor prognosis in gastric cancer patients." (PMID 40906383, 2025). "For example, TRIM25 promotes SP1 ubiquitination at K610, further inhibiting the expression of MMP2 and angiogenesis in gastric cancer." (PMID 40796546, 2025). "Matrix metalloproteinase-2 (MMP2) is an extracellular matrix protein involved in gastric cancer development." (PMID 40865948, 2025). "The same study revealed that inhibiting HMGB1 down-regulated Bcl-2 and MMP-2 but up-regulated Bax in gastric cancer cells." (PMID 40264171, 2025). "The potential of andrographolide lies in its ability to impede the progression of gastric cancer by suppressing MMP-2 and MMP-9 activities simultaneously enhancing TIMP-1 and TIMP-2 expression." (PMID 39583105, 2024). "Reducing the expression of HMGB3 leads to inhibition of invasion and migration of gastric cancer cells by suppressing the activation of MMP2 and MMP9." (PMID 39062899, 2024). "JP3 (an antiangiogenic peptide) modulates the TRIM25/SP1/MMP2 axis to suppress tumor growth, metastasis, and angiogenesis in gastric cancer." (PMID 38955795, 2024). "TRIM25 inhibits MMP2 expression by mediating the ubiquitination at K610 and degradation of SP1, the transcription factor of MMP2, thereby suppressing angiogenesis in gastric cancer." (PMID 39768197, 2024). "ATP5F1B, an RNA-binding protein, can enhance the proliferative and metastatic capacities of gastric cancer cells through the ATP-P2X7-FAK/AKT/MMP2 pathway." (PMID 38786611, 2024). "As reported, ATP5F1B, a novel RNA-binding protein, is involved in the proliferation and metastasis of gastric cancer cells via the ATP-P2X7-FAK/AKT/MMP2 axis." (PMID 38786611, 2024). "We found that the level of the secreted protein MMP2 in TAMs cocultured with gastric cancer cells was significantly increased compared with the level of the secreted protein MMP2 in normal TAMs." (PMID 35999359, 2023). "The low expression of CDK5RAP3 in gastric cancer cells promotes the secretion of MMP2 by macrophages, thereby enhancing the proliferation, invasion and migration ability of gastric cancer cells." (PMID 35999359, 2023).
gastric cancer (continued). "In order to explore the effect of MMP2 inhibitor on gastric cancer cells with downregulation of CDK5RAP3, we set up a group of gastric cancer cells with downregulation of CDK5RAP3 without macrophage co-culture." (PMID 35999359, 2023). "The downregulation of CDK5RAP3 in gastric cancer cells further increased the expression of MMP2 in macrophages, while overexpression of CDK5RAP3 significantly reduced the expression of MMP2." (PMID 35999359, 2023). "In human stomach cancer cells, up-regulation of AQP3 was associated with the increased expression of MMP2 and MMP9." (PMID 37143707, 2023). "The addition of an MMP2 inhibitor to the coculture system significantly inhibited the EMT process of gastric cancer induced by low expression of CDK5RAP3." (PMID 35999359, 2023). "The levels of serum MMP9 and MMP2 in patients with gastric cancer were significantly higher than normal people in clinical practice." (PMID 35069767, 2022). "In gastric cancer, MMP2, -3, -7, -9, -10, and -11 are upregulated in the course of disease progression, of which MMP2, -3, -7, and -9 have been suggested to have prognostic value for disease outcome." (PMID 35269560, 2022). "It was previously reported that LINC00473 suppressed migration and invasion of gastric cancer cells through regulating expression of Matrix metalloproteinase (MMP)‐2, MMP‐9, E‐cadherin, and Vimentin." (PMID 35600648, 2022). "A known antioxidant, N-acetyl-cysteine (NAC), suppressed expression of MMP such as MMP-9 and MMP-2, and cell invasion in pancreatic cancer cells, mammary epithelial cells, and gastric cancer cells." (PMID 36014933, 2022). "Others have been reported to have good potential to be prognostic biomarkers for CRC (CDKN1A, CDKN1B), stomach cancer (MMP2,) and esophageal cancer (EGFR, PIK3CA,)." (PMID 35681633, 2022). "Our in vitro results confirmed that THBS2 knockdown inhibited CD47 and MMP-2 expression and the progression of pancreatic and gastric cancers." (PMID 35701829, 2022). "They proved that melatonin suppressed cell growth by directly reducing ROS production, while indirectly decreasing the level of MMP2 and MMP9 in cancer-associated fibroblasts (CAFs) in gastric cancer cells." (PMID 36591447, 2022). "Chitosan can reduce the expression of cluster of differentiation 147 (CD147) and consequently MMP-2, thus showing a dose-dependent inhibition of metastasis of gastric cancer cells." (PMID 35267781, 2022). "Mechanistically, JWA promotes the degradation of specificity protein 1 (SP1) through the ubiquitin-proteasome pathway and then inhibits the expression of its downstream pro-angiogenic factor MMP2, ultimately inhibiting the angiogenesis of gastric cancer." (PMID 36230577, 2022). "PI3K/AKT/mTOR signaling is activated and induces MMP-9 expression in hepatocellular carcinoma and MMP-2 expression in gastric cancer cells." (PMID 36014933, 2022). "JWA has shown obvious inhibition of angiogenesis via downregulation of the expression of MMP2 in gastric cancer cells." (PMID 36230577, 2022). "The correlation between ATF1 mRNA and the mRNA levels of MMP2 was examined in gastric cancer cell lines and HEK293 cells." (PMID 35397606, 2022). "In conclusion, the present findings revealed a gastrin/CCK-BR autocrine/paracrine signaling loop in gastric cancer cells, which plays a significant role in the invasion and metastasis of cancer cells by promoting MMP-2 and VEGF expression." (PMID 34976177, 2022). "We investigated MMP-2 and MMP-9 expression and HERE-2/neu overexpression in 48 gastric cancer patients referred to Afzalipour Hospital, associated with Kerman Medical University." (PMID 33773545, 2021). "Based on the studies and the results of molecular docking, it can be concluded that with the receptors of hCA IX, MMP-2, gastric cancer, blood cancer WDR5, and HCC, the compound derived from CM, that is, OHC, tends to show the best activity." (PMID 34452553, 2021).
gastric cancer (continued). "Transfected SLPI‐siRNA in gastric cancer cell lines resulted in significantly reduced MMP2 and MMP9 expression, as well as cell migration and invasion rates." (PMID 34580954, 2021). "Studies have also shown that the migration and invasion of human gastric cancer cells SGC7901 can be inhibited by the P38MAPK signaling pathway through the expression of MMP-2 and MMP-9." (PMID 34127929, 2021). "Chemokine (C-X-C motif) ligand 1 (CXCL1) secreted by tumor-associated lymphatic endothelial cells induces integrin β1 to activate FAK/Akt signaling and promotes adhesion and metastasis of gastric cancer via MMP2/9 upregulation." (PMID 33406733, 2021). "What’s more, phosphor-ERK, MMP2/9, N-cadherin, Vimentin, Snail, Slug and Twist1 were downregulated and E-cadherin was upregulated in gastric cancer cells upon exposure to PD98059 at 0, 5, 10, 20 μM for 24 h." (PMID 34588421, 2021). "In summary, this study showed that SDF-1/CXCR7 enhanced the migration and invasion ability of the gastric cancer cells, increased expressions of MMP-2, MMP-9 and VEGF, promoted EMT and activated the Akt pathway." (PMID 34858476, 2021). "Dihydromyricetin (DHM) up-regulates E-cadherin and down-regulates Vimentin through the JNK/MMP-2 pathway, inhibiting the migration and invasion of gastric cancer cells." (PMID 34422902, 2021). "The invasion and migration of gastric cancer cells can be promoted by MMP-2 and MMP-9, which are upregulated by the CXCL10/CXCR3 axis." (PMID 34367971, 2021). "CAF-derived exosomes taken up by scirrhous-type of gastric cancer but not in the other types; CD9-positive CAF-derived exosomes promoted migration and invasion in scirrhous-type gastric cancer cells through MMP-2 activation." (PMID 32957712, 2020). "Recent study shows that miR-29b negatively regulates MMP2 expression and activity to suppress gastric cancer cell migration and tumor growth." (PMID 32600379, 2020). "Here we demonstrated that JP3 plays a role in inhibiting angiogenesis, proliferation and metastasis of gastric cancer through down-regulating MMP2." (PMID 32576271, 2020). "Subsequent studies have shown that gastric cancer cells infected by Helicobacter pylori increase the activity of MMP-2, MMP-9, and MMP-10 through c-Met- and EGFR-dependent signaling pathways, inducing ECM remodeling and cell invasion." (PMID 32046329, 2020). "For example, Propofol impeded the proliferation and motility of gastric cancer cells through targeting miR-29/MMP2 signaling." (PMID 33126850, 2020). "CD9+ CAF-derived exosomes stimulate migration and invasion in scirrhous-type gastric cancer cells, and promote increased MMP-2 activity." (PMID 32957712, 2020). "WISP2 regulated cell growth, migration, and metastasis by regulating EMT and inhibiting matrix metalloproteinase (MMP)-9 and MMP-2 via ERK in gastric cancer cells." (PMID 32711570, 2020). "In human gastric carcinoma AGS cells antimetastatic effect was mediated via the inhibition of MMP-2 secretion." (PMID 32028623, 2020). "Here, TSLL successfully suppressed the migration and invasion of gastric carcinoma cells by decreasing the expression of MMP-2 and elevating the expression of TIMP-1." (PMID 32368309, 2020). "Our previous study has also demonstrated that LOX and MMP-2 expression are positively correlated in tissues from gastric cancer patients." (PMID 31777578, 2019). "WISP2 downregulation promoted cell growth, migration and invasion, but WISP2 overexpression suppressed cell metastasis through regulation of EMT and inhibition of MMP-9 and MMP-2 via ERK in gastric cancer cells." (PMID 30808397, 2019). "In gastric cancer, MMP-2/-9 are over-expressed and closely correlated with the metastasis of patients." (PMID 31632484, 2019). "After LOX were inhibited with different concentrations of BAPN in BGC-823 gastric cancer cells, the protein concentrations and enzyme activity levels of MMP-2 and MMP-9 in the culture supernatants were decreased (P < 0.05)." (PMID 31777578, 2019).
gastric cancer (continued). "Published in vitro studies showed that the overexpression of miR-29b significantly decreased the mRNA and protein level of MMP2 and the activity of MMP2 to suppress gastric cancer cell migration." (PMID 30884856, 2019). "As2O3 has also been demonstrated to inhibit migration by regulating the expression of Cox-2/PGE2/MMP-2 in gastric cancer cells, and increased ROS played a critical role in this effect." (PMID 30477221, 2018). "We found that Zey suppressed the metastasis of gastric cancer cells by decreasing protein levels of MMP-2 and MMP-9 and inhibiting the phosphorylation of AKT, ERK, and mTOR." (PMID 30150551, 2018). "Recently, activation of ERK signaling pathway was reported to increase MMP2 expression and promote gastric cancer cells invasion." (PMID 29262634, 2017). "MMP-2 is one of the important enzymes for degrading type IV collagen in the invasion and metastasis of gastric cancer." (PMID 29358963, 2017). "Given a critical role of matrix metalloproteinases (MMPs) in cell migration and invasion, we next tested the effect of AIB1 down-regulation on the expression of MMP-2, -7, -9 and -14 genes in gastric cancer cells." (PMID 25970779, 2015). "Another study has reported that OPN promotes the progression of gastric cancer by activating matrix metalloproteinase 2 (MMP-2) and MMP-9 through the NF-kappaB pathway." (PMID 26289107, 2015). "The mechanisms of NKD2 in gastric cancer cell invasion and migration were further investigated by detecting the expression of MMP-2 and MMP-9." (PMID 26396173, 2015). "Further study found that SOX18 promotes cell invasion and metastasis by down regulating MMP-2,7,9 in gastric cancer cells." (PMID 26396173, 2015). "Taken together, our results suggest that M2-like macrophages are more efficient than their M1 counterparts in stimulating gastric cancer cell invasion, likely due to their increased MMP-2 and MMP-9 activity and higher ability to promote cancer cell migration." (PMID 26043921, 2015). "In the present study, the expression of HIF-1α, MMP-2, MMP-9, bFGF and uPA was detected in order to further reveal the underlying mechanism of the function of the KAI1 gene in gastric cancer." (PMID 26622792, 2015). "H2S inhibits cell migration (the initial step for cell invasion) and MMP-2 expression (critical step for cell invasion) and, therefore, blocks gastric cancer cell invasion." (PMID 26078811, 2015). "Consistent with these previous studies, the present study demonstrated that ursolic acid inhibits the invasive phenotype of SNU-484 gastric cancer cells by downregulating MMP-2 expression." (PMID 25621065, 2015). "The expression of MMP-2 was significantly increased in gastric carcinoma SGC7901 cells by KAI1 expression, whereas the expression of uPA was significantly downregulated." (PMID 26622792, 2015). "The aptamer showed high affinity for MMP2 (Kd = 5.59 nM), precipitated MMP2, and detected MMP2 protein in pathological tissues such as atherosclerotic plaque and gastric cancer tissues." (PMID 24589243, 2014). "Increased MMP-2 activity is considered to be important for the increased capability of gastric cancer cells to traverse the membrane and invade and metastasize to distant sites." (PMID 24959277, 2014). "Previous specific studies have suggested a major role for MMP-2 and -9 in the digestion of basement membrane type IV collagen, as an important mechanism for vessel invasion and metastasis in gastric cancer." (PMID 25120725, 2014). "In our previous study, immunohistochemistry was used to examine the expression levels of claudin-4 and MMP-2 and -9 in 189 gastric cancer samples, and their correlation with tumor invasion and clinicopathological parameters was analyzed." (PMID 25120725, 2014). "It was reported that the upregulation of transgelin in stromal fibroblasts promoted gastric cancer cell migration and invasion by inducing the expression of matrix metalloproteinase-2 (MMP-2)." (PMID 25109740, 2014).